HIF1A (hypoxia inducible factor 1 subunit alpha)
Diseases named in the same sentence as HIF1A in open-access papers (continued):
Sharing a sentence is not in itself a finding about the gene and the disease.
lung carcinoma (continued). "Deletion of Otulin with two pairs of siRNAs increased HIF1α expression in A549 and NCI-H460 lung cancer cells." (PMID 38272870, 2024). "The expression level of HIF-1α in patients with lung cancer was evaluated using the UALCAN database and TissueScan lung cancer cDNA arrays." (PMID 38880883, 2024). "To verify the effect of ROS and succinate on HIF-1α and PHD2 expression in lung cancer cells, we aimed to increase the levels of ROS and succinate within the cells." (PMID 38880883, 2024). "This study confirmed that IH regulates the interaction between mtROS and CSCs by mediating HIF-1α/ATAD2, promoting lung cancer progression." (PMID 38605948, 2024). "Since knockdown of PDLIM2 leads to the accumulation of mtROS and succinate, we further investigated the protein levels of HIF-1α and PHD2 in PDLIM2 knockdown lung cancer cells." (PMID 38880883, 2024). "The expression levels of the top five lung cancer genes, CTNNB1, STAT3, HIF1A, HSP90AA1, and ERBB2, were determined by comparing them with the LUAD and LUSC datasets using the GEPIA2 web server." (PMID 39113883, 2024). "Altogether, our findings suggest that PRMT5 regulates lung cancer cell EMT and metastasis, at least in part, via promoting angiogenesis by controlling HIF-1α/VEGFR/Akt/eNOS signaling pathway." (PMID 37400960, 2023). "LPE displayed the maximum anticancer effect on rat primary lung cancer with the downregulation of VEGF and HIF-1α and the improvement of cancer cell apoptosis after intratracheal administration." (PMID 37538179, 2023). "Recent studies have demonstrated that interaction and phosphorylation of SOX2 by CDK1 positively regulate stemness in lung cancer, and CDK1 phosphorylation of both HIF-1α and EZH2 promotes tumor cells survival and proliferation." (PMID 37189841, 2023). "In lung cancer, high expression of HSP70s has been found to promote SUMO modification of hypoxia-inducible factors-1α (HIF-1α) and consequently promote EMT in tumor cells." (PMID 38062023, 2023). "To explore the potential function of HIF-1α and PRMT5 in lung cancer, we first evaluated the mRNA expression of HIF-1α in PRMT5 depletion cells." (PMID 37400960, 2023). "In this study, we investigated the role of SIRT3 on tumor development in lung cancer cells and tumor-forming nude mice via the ROS-FPR1/HIF-1α axis in a hypoxic environment." (PMID 37747648, 2023). "Previous studies have found that HIF-1α is involved in the angiogenesis of non-small cell lung cancer, and the expression levels of HIF-1 and VEGF in lung cancer were significantly higher than those in the adjacent normal tissues." (PMID 36439496, 2022). "Our findings indicate that STIL promotes tumor metastasis through the HIF1α-STIL-FOXM1 axis, and highlight the importance of STIL as a promising therapeutic target for lung cancer treatment." (PMID 35365182, 2022). "SIRT1, HIF1α and VEGFA protein expression in DDP-induced chemotherapy-resistant lung cancer tissues were declined when miR-326 was overexpressed." (PMID 34696659, 2022). "HIF‐1α was also found to both modulate ALDOA expression and increase lactate levels, leading to upregulation of MMP9, thereby promoting an invasion of lung cancer cells in vitro and in vivo." (PMID 35615976, 2022). "Previous studies have reported that NDUFA4 promotes the progression of lung cancer cells via activating PI3K/AKT pathway and the PI3K/AKT pathway is responsible for glycolysis by regulating HIF-1α target genes ENO1 and LDHA." (PMID 35977935, 2022). "Thus, cells like pancreatic cancer, liver cancer, and lung cancer can activate the transcription of many genes, including those involved in energy metabolism, angiogenesis, and other protein products, by producing HIF1α to increase oxygen delivery or promote metabolic adaptation to hypoxia." (PMID 35860430, 2022).
lung carcinoma (continued). "It was demonstrated that CASC9 can be induced by HIF-1α and promote the stability of HIF-1α, indicating that HIF-1α and CASC9 can form a mutual activation pathway to promote the progression of lung cancer (Table A1)." (PMID 36139386, 2022). "For instance, a HIF-1α-specific lncRNA can directly regulate the stability of HIF-1α mRNA and thus confer poor prognosis in lung cancer." (PMID 35801079, 2022). "Our results showed that the HIF1α intensity was positively correlated with the expression of STIL (Pearson’s co-efficient, R = 0.54) in lung cancer specimens." (PMID 35365182, 2022). "The mechanism of action of HIF-1α in lung cancer, HIF-1α targets, and HIF-1α pharmacology are of significant interest to researchers." (PMID 36338690, 2022). "Ellagic acid (EA), a naturally occurring polyphenolic compound found in many vegetables and fruits, reduces the protein expression and activation of HIF-1α and the transcriptional levels of HIF-1α-targeted genes in lung cancer cells." (PMID 36139386, 2022). "There are also reports that ASA inhibits hypoxia-induced stemness in A549 lung cancer cells and promotes EMT via HIF-1α-mediated transactivation of EMT-inducing factors." (PMID 35892853, 2022). "Among these, the negative regulation of HIF-1α/VEGF axis, tumor growth and microvessel density in lung cancer has been reported when Sema3F was overexpressed." (PMID 33858502, 2021). "A study using a lung cancer cell line showed that inflammatory IL-1β can activate NFκB, which in turn activates the COX-2/HIF-1α/VEGF angiogenic axis." (PMID 34094895, 2021). "Wnt3a/β-catenin, circSATB2, HIF-1α/COX-2, KLF9, and LMO7 in tumor-derived exosomes regulate genes or signaling pathways to promote proliferation and migration of lung cancer cells." (PMID 34511114, 2021). "Our results demonstrate that NuF can promote the anticancer effect of lung cancer to targeted therapy, especially in Iressa, by inhibiting HIF-1α and epithelial-mesenchymal transition (EMT) and inducing the apoptosis of lung cancer cells." (PMID 34064322, 2021). "In lung cancer, AK4 operates as an upstream HIF-1α regulator by stabilizing HIF-1α through the inhibition of its hydroxylation and subsequent degradation, whereas in macrophages it acts by enhancing both HIF-1α gene transcription and protein stability." (PMID 34638712, 2021). "To investigate the conservation of the acute transcriptional response to hypoxia, we repeated RNA-seq and HIF1A ChIP-seq analyses for three additional cancer cell types: RKO (colorectal carcinoma), A549 (lung cancer), and H460 (lung cancer) (, 5)." (PMID 33654095, 2021). "A decrease in HIF-1α and GLUT1 expression was detected in lung cancer xenografts treated with β-elemene." (PMID 34575983, 2021). "Bioinformatic analysis revealed the synergistic effect between the Set7/9 and either HIF1A, HK2, GLUT1, or LDHA expression levels on the survival outcome of lung cancer patients." (PMID 34692483, 2021). "Alternative molecular mechanisms for HIF-1α overexpression in HEU vs. UU should be elucidated, as occurs in other clinical contexts such as lung cancer." (PMID 34211989, 2021). "Bioinformatic analysis has shown a synergistic impact of Set7/9 together with either GLUT1, HIF1A, HK2, or LDHA on the survival of lung cancer patients." (PMID 34692483, 2021). "We determined HIF-1α level in lung cancer tissues and normal tissues and tested a higher level of HIF-1α in lung cancer tissues." (PMID 34044859, 2021). "In a lung cancer cell line, PGE2 induced HIF-1α and expression of proangiogenic vascular and endothelial growth factor (VEGF)." (PMID 34094895, 2021).
lung carcinoma (continued). "It has also been found that HIF‐1α is associated with angiogenesis in non‐small‐cell lung cancer (NSCLC), and the expression of HIF‐1α and VEGF are positively correlated and significantly higher in lung cancer tissues compared with normal tissues." (PMID 34387383, 2021). "According to our previous findings, inhibition of HIF-1α significantly downregulated the expression of GLUT1 at both the protein and mRNA levels in lung cancer cells." (PMID 33282728, 2020). "HB-EGF expression were upregulated in As-T cells, lung cancer cell lines, and in most lung cancer tissue samples; and HB-EGF activated the EGFR/p-ERK/HIF-1α pathway and induced VEGF by regulating HIF-1α transcription." (PMID 32695675, 2020). "The aim of current study was to elucidate the regulatory mechanism between HPV16E6/E7, PTEN, TXNIP, HIF-1α, and GLUT1 in lung cancer cells and provide a new strategy for the treatment of HPV-related lung cancer." (PMID 33282728, 2020). "In lung cancer, a report has shown that DAXX can inhibit cancer cell metastasis by directly blocking the HIF1a/HDAC1/Slug signaling pathway." (PMID 31942198, 2020). "Cobalt chloride (CoCl2) was adopted to mimic a hypoxic microenvironment and western blot was used to detect the expression of hypoxia inducible factor-1α (HIF-1α), VEGFA and ANGPT2 in lung cancer cell lines." (PMID 31892982, 2020). "The relationship between HIF-1/2α and EMT is now clearly demonstrated, and the links between HIF-1α expression, EMT, and generation of distant metastases, for example in advanced lung cancer, are established." (PMID 32290283, 2020). "The expression of PD-L1 is significantly related to Glut1, HIF-1α and SUVmax on 18F-FDG uptake in lung cancer." (PMID 32156047, 2020). "For instance, in a murine model of lung carcinoma, DHA suppressed expression of the HIF-1a/VEGF axis and decreased tumor size with cisplatin treatment." (PMID 32290307, 2020). "In this study, we obtained eight lung cancer-related genes (CDC25C, TWIST1, HIF1A, DNMT1, PARP1, CDKN1A, CCNB1, and BIRC5) as seed nodes, using an RWR algorithm analysis to prioritize lung cancer related genes." (PMID 33193600, 2020). "In this study, we constructed a nude mouse xenograft model of lung cancer and administered apatinib at different doses and times to detect the normalization of reactive blood vessels through VEGF, α‐SMA, college‐IV, HIF‐1α, and MMP." (PMID 32073228, 2020). "Our results provided new molecular mechanisms in HPV16 E6/E7 promoted the glucose uptake by relieving TXNIP inhibitory effect on HIF-1α and GLUT1 in lung cancer cells." (PMID 33282728, 2020). "In vivo lung cancer cells, sulfated fucoidan extract was able to inhibit the tumor growth in vitro but via the reduction of expression of VEGF or HIF-1a." (PMID 30621045, 2019). "In lung cancer cells, it exerts anti-angiogenesis activity by suppressing CoCl2- and EGF-induced VEGF protein production, mRNA expression, HIF-1α expression, and HRE promoter activity." (PMID 30871059, 2019). "In our previous studies, we found that HPV16 E6/E7 up-regulated HIF-1α at protein level and further up-regulated GLUT1 at both protein and mRNA levels in well-established lung cancer cell lines." (PMID 31839825, 2019). "The inhibitor of HIF-1α (FIH) is downregulated by miR-31-5p; thus, miR-31-5p promotes lung cancer progression via enhancing glycolysis." (PMID 30935143, 2019). "In lung cancer cell lines, ectopic PLOD2 expression rescued the migration and metastasis defects resulting from HIF-1α silencing, and the defects were again reinstated by concomitant inhibition of PLOD2 activity." (PMID 31446433, 2019). "Here, we identified a novel signaling axis whereby enhanced expression of AK4 exaggerates HIF-1α protein expression, leading to EMT induction in lung cancer." (PMID 30696468, 2019).
lung carcinoma (continued). "We have previously found that NTHi-induced COPD-like airway inflammation upregulates HIF-1α and vascular endothelial growth factor (VEGF) gene expression in the whole lung of a K-ras mutant mouse model of lung cancer (CC-LR or CCSPCre/LSL–KrasG12D mouse)." (PMID 30250643, 2018). "Collectively, these results indicate that miR‐18a‐5p increases the radiosensitivity in lung cancer cells and CD133+ stem‐like cells via downregulating ATM and HIF‐1α expressions." (PMID 29860718, 2018). "In addition, it is discussed that HIF-1α might be a target for therapy in lung cancer." (PMID 29983647, 2018). "This supports the epithelial HIF-1α pathway activation as an essential process for the transition between COPD and lung cancer." (PMID 30250643, 2018). "The purpose of our study is to elucidate the effects of HIF‐1α and CAIX on chemoresistance and prognosis of lung cancer patients after induction chemoradiotherapy, and finally to improve them." (PMID 28028936, 2017). "We investigated the effect of HIF‐1α and carbonic anhydrase IX (CAIX), a transmembrane protein neutralizing intracellular acidosis, on chemoresistance and prognosis of lung cancer patients after induction chemoradiotherapy." (PMID 28028936, 2017). "It is possible as well that in the lung cancer setting, UCP2 and PRPF40A act upstream of hypoxia pathways, thus inducing expression of HIF1α independently of the O2 tension." (PMID 28258342, 2017). "Immunohistochemical analyses were performed to determine HIF‐1α, GLUT1, and CAIX expression levels in cancer specimens from lung cancer patients after induction chemoradiotherapy." (PMID 28028936, 2017). "Here, we observed that the expression levels of p-AKT, HIF-1α and VEGF in miR-137-expressing lung cancer cells were both downregulated, but elevated in miR-137-inhibitor expressing lung cancer cells." (PMID 26989074, 2016). "In summary, we demonstrated that Daxx plays a pivotal role in hypoxia-induced cancer cell dissemination and invasion by regulating the HIF-1α/HDAC1/Slug and E-cadherin pathway in lung cancer." (PMID 28004751, 2016). "In our recent work in both human and mouse lung cancer cells in culture, we found that EGCG specifically upregulated the expression of mir-210, a major microRNA regulated by HIF-1α." (PMID 27941682, 2016). "As the key stimulator of HIF-1α, oxygen deprivation led to DDP and doxorubicin resistance in lung cancer cells." (PMID 27323827, 2016). "Our study showed that the BBR inhibited HIF-1α expression, thereby inhibited the VEGF/PEDF ratio in lung cancer cells." (PMID 23869238, 2013). "We next determined the effect of BBR on the expression of HIF-1α, VEGF and PEDF at protein and mRNA levels in lung cancer cells by RT-PCR and Western blot, respectively." (PMID 23869238, 2013). "MUC1, a physiological marker, HIF1A, a regulator of metabolic reprogramming, and NKX2-1, a lineage-specific marker performed well as classifiers of lung cancer and its major subtypes." (PMID 23028920, 2012). "The lung cancer cell lines EPLC-272H and H1339 were chosen because they differ in their basal HIF-1α levels but show comparable intrinsic resistance towards irradiation or drug alone." (PMID 22347438, 2012). "In contrast, treatment of H1339 lung carcinoma cells with NVP-AUY922 and 17-AAG resulted in a significant up-regulation of their initially high HIF-1α levels and a concomitant increase in radiosensitivity." (PMID 22347438, 2012). "HIF-1α regulates xeroderma pigmentosum, complementation group A (XPA) expression and contributed to cisplatin resistance in lung cancer." (PMID 23241400, 2012). "Herein, HIF-1α and HIF-2α protein levels were analyzed in EPLC-272H and H1339 lung cancer cells under normoxic ([O2] = 21%) and hypoxic ([O2] = 0.66%) conditions, in the presence and absence of two structurally distinct Hsp90 inhibitors, 17-AAG and NVP-AUY922." (PMID 22347438, 2012).
lung carcinoma (continued). "Moreover, our study delineated the interplay between HIF1A and ferroptosis upon YFJDT treatment in regulating lung cancer progression." (PMID 39912781, 2025). "Additionally, the combination of Rg3 and cisplatin increases cisplatin sensitivity and enhances its therapeutic effect on tumors by downregulation of HIF-1α expression and inhibiting tumor cell EMT in hypoxic lung cancer cells." (PMID 41585262, 2025). "In agreement, it was observed that miR-214 enhances HIF-1α expression, supporting invasion in NSCL, and miR-18, miR-200c, and miR-549 significantly downregulate both transcript and protein levels of HIF-1α in lung carcinoma cells." (PMID 40869000, 2025). "Clinical Implications (Lung cancer): METTL3 inhibition is best suited for tumors demonstrating METTL3-dependent, eIF3h-facilitated translational activation and IGF2BP-mediated stabilization of MYC or HIF-1α pathways." (PMID 41515964, 2025). "Specifically, the investigation revealed a connection between the phytochemical constituents and the genes CTNNB1, STAT3, HIF1A, HSP90AA1, and ERBB2, which have established links to lung cancer and play essential roles in the critical cellular pathways involved in disease progression." (PMID 39113883, 2024). "In addition, an increasing number of studies have shown that HPV plays a role in the carcinogenesis, development and progression of lung cancer through several signaling pathways, such as the PI3K/Akt/HIF-1α pathway." (PMID 38913637, 2024). "Knockdown of HOIP with two pairs of HOIP siRNA reduced HIF1α expression in A549 lung carcinoma cells and HEK293T cells (data not shown)." (PMID 38272870, 2024). "This interaction highlights the importance of the NCL/CAMSAP3 relationship in regulating aggressive metastatic and angiogenic tendencies in lung cancer cells, establishing CAMSAP3 as a key suppressor in lung cancer progression by influencing the NCL/HIF‐1α mRNA complex." (PMID 39304978, 2024). "Notably, our findings reaffirm the relevance of lung cancer genes, such as CTNNB1, STAT3, HIF1A, HSP90AA1, and ERBB2, integral to various cellular processes and pivotal in cancer genesis and advancement." (PMID 39113883, 2024). "Additionally, research indicates that CAFs in lung cancer, through HIF-1α, increase the expression of stearoyl-CoA desaturase 1 (SCD1), thereby increasing the number of lipid droplets in cells and promoting lung cancer growth." (PMID 39769177, 2024). "Our findings indicate that PRMT5 promotes lung cancer epithelial-mesenchymal transition (EMT), which might be possibly through controlling the HIF-1α/VEGFR/Akt/eNOS signaling axis." (PMID 37400960, 2023). "Additionally, we found that the expression levels of HIF-1α and its binding protein HSP70 were increased after insufficient RFA in the lung cancer mouse model." (PMID 37948404, 2023). "First, statistical analyses of HIF-1α expression and the tumor microenvironment in human lung cancer with IP were not performed." (PMID 38012636, 2023). "Treatment with CCNPs improved the effect of chrysin on succinate-ubiquinone oxidoreductase activity and expression and therefore has the potential as a more efficient formulation than chemotherapy to prevent metastasis and angiogenesis by targeting HIF-1α in PDAC and lung cancer." (PMID 36906524, 2023). "Moreover, we showed elevated expression of HIF-1α and carbonic anhydrase IX (CA-IX), a well-known HIF-target gene in biopsies of BM from lung cancer." (PMID 38006431, 2023).